BIRC6 (baculoviral IAP repeat containing 6)
Diseases named in the same sentence as BIRC6 in open-access papers (continued):
Sharing a sentence is not in itself a finding about the gene and the disease.
colorectal cancer (9 papers, 2015 to 2025). A primary or metastatic malignant neoplasm that affects the colon or rectum. "Other studies have also shown a significant association of BIRC6 overexpression with tumor size and invasion depth in colorectal cancer and childhood AML." (PMID 40510224, 2025). "The gene has been suggested to be a prognosis predictor in colorectal cancer and BIRC6 mutations have been found in colorectal adenomas and are common in carcinomas." (PMID 30809968, 2019). "We also demonstrated that high expression of BIRC6 was associated with adverse clinical and pathologic features in colorectal cancer." (PMID 25933218, 2015). "At present, most people are familiar with the BIRC6 gene in tumors, such as non-small cell lung cancer, bladder cancer, colorectal cancer, and others." (PMID 37189611, 2023). "In the present study, we explored the prognostic significance and biologic features of BIRC6 in colorectal cancer." (PMID 25933218, 2015). "Here we explored the role of baculoviral IAP repeat containing 6 (BIRC6), a member of IAPs, in human colorectal cancer (CRC)." (PMID 25933218, 2015). "Furthermore, evidence demonstrates the overexpression of BIRC6 in various types of cancer, including colorectal cancer, brain cancer, childhood de novo acute myeloid leukemia, hepatocellular carcinoma, and human epithelial ovarian cancer." (PMID 38066801, 2023). "In addition, overexpression of BIRC6 has been found in various tumors, including colorectal cancer, gastric carcinomas, and lung cancer." (PMID 36105077, 2022). "Taken together, these data suggests that BIRC6 overexpression is a predictor of poor prognosis in colorectal cancer and BIRC6 could be a potential target of CRC therapy." (PMID 25933218, 2015). "In the present study, we observed that the expression of BIRC6 could be detected in both colorectal cancer and adjacent tissues but with different percentage." (PMID 25933218, 2015). "In addition, BIRC6 was shown to promote the progression of prostate, liver and colorectal cancers." (PMID 31692446, 2019). "Although the previous study demonstrated that BIRC6 was up-regulated in colorectal cancer using cDNA microarray and qRT-PCR analysis, the relationship between BIRC6 expression and colorectal cancer progression has not been extensively studied." (PMID 25933218, 2015). "Online databases Oncomine and GEPIA were used to compare the expression of IAPs (NAIP, BIRC2, BIRC3, XIAP, BIRC5/survivin, BIRC6 and BIRC7, no data on BIRC8 was available) between colorectal cancer and normal tissues." (PMID 32381104, 2020).
lung cancer (9 papers, 2013 to 2025). A malignant neoplasm involving the lung. "Although previous studies have shown a significant association between BIRC6 expression and lymph node involvement in lung cancer, lymphoma, thyroid cancer, and esophageal squamous cell carcinoma, the higher the BIRC6 serum level, the more lymph node involved in the disease." (PMID 36033570, 2022). "XIAP (BIRC4), Survivin (BIRC5), Livin (BIRC7), and BRUCE or Apollone ((BIRC6) are four members of the IAP family that play an important role in the development of chemoresistant lung cancer." (PMID 36800962, 2023). "Furthermore, our in vivo preclinical results demonstrated that the BIRC6-silencing baculovirus was able to significantly reduce the tumor growth rate in both experimental models of breast and lung cancer." (PMID 41305480, 2025). "Additionally, in our mice experimental model of lung cancer, the BIRC6-silencing baculovirus significantly increased survival." (PMID 41305480, 2025). "Moreover, PRIS also decreased expression of BIRC6, which is a caspase inhibitor that has recently been shown to be overexpressed in different types of cancer such as lung cancer." (PMID 32733636, 2020).
gastric cancer (8 papers, 2016 to 2025). A primary or metastatic malignant neoplasm involving the stomach. "Moreover, as the host gene of miR-558,21 baculoviral IAP repeat containing 6 (BIRC6) was positively correlated with HPSE levels in gastric cancer cases derived from Gene Expression Omnibus datasets." (PMID 27685626, 2016). "Additionally, the BIRC6 levels were increased in gastric cancer specimens derived from public datasets." (PMID 27685626, 2016).
hepatocellular carcinoma (7 papers, 2018 to 2025). A malignant tumor that arises from hepatocytes. "Circ_BIRC6 overexpression relieved PTX-induced repression of hepatocellular carcinoma progression through trapping miR-877-5p." (PMID 34649611, 2021).
melanoma (7 papers, 2008 to 2024). A malignant, usually aggressive tumor composed of atypical, neoplastic melanocytes. "In this study, the transcript levels of IAP genes including NAIP (BIRC1), BIRC2 (CIAP1), BIRC3 (CIAP2), BIRC5 (Survivin), BIRC6 (Apollon), and XIAP (BIRC4) in UA-treated A-375 melanoma cells were investigated." (PMID 39473730, 2024).
cervical cancer (4 papers, 2017 to 2023). A primary or metastatic malignant neoplasm involving the cervix. "In our cervical cancer data, the mutated genes involved in this pathway included FBXW7 (altered in 17%), HUWE1 (altered in 13%), and BIRC6 (altered in 9%)." (PMID 27998038, 2017). "In cluster 1/2, the incidence of FLG, BIRC6, and IGSF10 mutations were significantly higher, and it is reported that FLG contributes to the biological activity of barrier function and associates with the poor prognosis of cervical cancer." (PMID 37735483, 2023).
lymph node metastasis (4 papers, 2014 to 2025). "Increased BIRC6 expression in non-small cell lung cancer (NSCLC) is linked to an advanced pathological T stage, poor differentiation, and lymph node metastasis, and may be associated with tumor progression." (PMID 37781078, 2023). "The results of other studies have shown more advanced pathological T stage, poor differentiation, and lymph node metastasis in cases with BIRC6 overexpression in NSCLC and esophageal squamous cell carcinomas, compared with those with low expression of BIRC6." (PMID 40510224, 2025).
neuroblastoma (4 papers, 2012 to 2024). Neuroblastoma (NB) is the most common solid, extracranial childhood tumor. "We therefore investigated which process causes apoptosis after BIRC6 silencing in neuroblastoma." (PMID 22788920, 2012). "Co-immunoprecipitation confirmed direct interaction between DIABLO and BIRC6 in neuroblastoma cell lines." (PMID 22788920, 2012). "We therefore investigated whether the high BIRC6 expression allows neuroblastoma cells to survive the high levels of the pro-apoptotic protein DIABLO." (PMID 22788920, 2012). "Our findings indicate that BIRC6 may have a potential oncogenic role in neuroblastoma by inactivating cytoplasmic DIABLO." (PMID 22788920, 2012). "BIRC6, which is located on 2p22, is gained in 24% of the neuroblastoma tumors." (PMID 22788920, 2012). "These experiments suggest that BIRC6 may effectively inactivate cytoplasmic DIABLO in neuroblastoma cells and can thereby prevent an apoptotic response." (PMID 22788920, 2012). "BIRC6 is located on chromosome 2p in the region which shows frequent gain in neuroblastoma." (PMID 22788920, 2012). "We investigated whether the high BIRC6 levels indeed counteract apoptosis in neuroblastoma." (PMID 22788920, 2012). "BIRC6 inhibition may therefore provide a means for therapeutic intervention in neuroblastoma." (PMID 22788920, 2012). "This is consistent with our recent discovery that Survivin is a target for autophagosomal removal in neuroblastoma and our results are in line with data on another IAP, BIRC6/BRUCE, which is also degraded via autophagosomal removal." (PMID 28415610, 2017). "This indicates that this process is not CASP2-mediated, implying that the role of BIRC6 in neuroblastoma is not essential for completion of cell division during midbody ring formation." (PMID 22788920, 2012). "Since BIRC6 was not previously evaluated in a neuroblastoma model, we studied the potency of BIRC6 as a potential new target for neuroblastoma therapy." (PMID 22788920, 2012). "To test this hypothesis, we first investigated by a co-immunoprecipitation analysis whether BIRC6 and DIABLO physically interact in neuroblastoma cells." (PMID 22788920, 2012).
ovarian carcinoma (4 papers, 2022 to 2025). A malignant neoplasm originating from the surface ovarian epithelium. "Mutations of CACNA1D and BIRC6 in ovarian cancer were first reported in our study." (PMID 36081665, 2022). "Studying the expression level of BIRC6 in epithelial ovarian cancer cells compared with normal tissue by Western blot showed a higher BIRC6 expression in the carcinoma tissue than in normal control tissue." (PMID 40510224, 2025).
esophageal squamous cell carcinoma (3 papers, 2022 to 2025). Esophageal squamous cell carcinoma (ESCC) is a type of esophageal carcinoma (EC) that can affect any part of the esophagus, but is usually located in the upper or middle third. "Consistently, BIRC6 overexpression has been reported in several cancer types, including triple-negative breast cancer, prostate, renal, colorectal, childhood acute myeloid leukemia, ovarian, hepatocellular, esophageal squamous cell carcinoma, and non-small cell lung cancer (NSCLC)." (PMID 41305480, 2025).
glioma (3 papers, 2013 to 2015). A benign or malignant brain and spinal cord tumor that arises from glial cells (astrocytes, oligodendrocytes, ependymal cells). "Elevated levels of BIRC6 have been linked to apoptosis resistance, for instance in the SNB-78 glioma cell line and over-expression of BIRC6 in human fibrosarcoma cells supports resistance to anti-cancer drugs and death receptor ligation." (PMID 23409057, 2013).
oral squamous cell carcinoma (3 papers, 2022 to 2025). "This study is aimed at investigating the presence of BIRC6 as a biomarker in oral squamous cell carcinoma." (PMID 36033570, 2022). "More in-depth studies for evaluating BIRC6 serum levels in oral squamous cell carcinoma patients are recommended for better insight into this protein's role in diagnosing, progression, and prognosis of the disease." (PMID 36033570, 2022). "Ma and colleagues found a significant association between BIRC6 expression with cancer metastasis and lymph involvement; however, this is not applicable in oral squamous cell carcinoma." (PMID 36033570, 2022). "This study is aimed at assessing the serum level of BIRC6 in oral squamous cell carcinoma." (PMID 36033570, 2022). "Therefore, we recommend a more extensive investigation on BIRC6 expression in the tissue and serum with a bigger sample size of oral squamous cell carcinoma and different test types." (PMID 36033570, 2022). "Therefore, for better generalization, we recommend a more in-depth study of the subject matter using a larger sample size using different molecular tests in order to understand the role of BIRC6 serum level and expression in oral squamous cell carcinoma." (PMID 36033570, 2022). "Others have also shown upregulation and overexpression of BIRC6 in oral lichen planus (with and without dysplasia), hyperkeratosis, oral squamous cell carcinoma, and oral epithelial dysplasia." (PMID 40510224, 2025).
pancreatic cancer (3 papers, 2009 to 2018). "Pamrevlumab has also been found to downregulate pro-survival factors XIAP and BIRC6 in a model of pancreatic cancer and the related inhibitor of apoptosis BIRC5 was among the RT-elevated, pamrevlumab-diminished genes identified in the current model." (PMID 29347981, 2018). "Interestingly, germline amplification of BIRC6 was found in patients with a family history of pancreatic cancer." (PMID 19759907, 2009).
breast tumors (2 papers, 2015 to 2025). "BV-based silencing of BIRC6 may have therapeutic value for the treatment of lung and breast tumors." (PMID 41305480, 2025).
acute promyelocytic leukemia (1 paper, 2012). An aggressive form of acute myeloid leukemia (AML), characterized by arrest of leukocyte differentiation at the promyelocyte stage, due to a specific chromosomal translocation t(15;17) in myeloid cells. "Moreover, BIRC6 expression significantly increased during neutrophil differentiation of AML cell lines and knocking down BIRC6 in NB4 acute promyelocytic leukemia (APL) cells significantly impaired neutrophil differentiation, but not cell viability." (PMID 23211188, 2012).
adenoma (1 paper, 2013). A neoplasm arising from the epithelium. "BIRC6, which was found to be mutated in the adenoma, is an ubiquitin-conjugating enzyme (E2) and involved in the apoptosis process." (PMID 23301059, 2013).
astrocytoma (1 paper, 2025). "Because the father was WT for BIRC6, the patient’s homozygous status must have resulted from a novel second mutation and led to astrocytoma development." (PMID 40995433, 2025).
autism (1 paper, 2025). Persistent deficits in social interaction and communication and interaction as well as a markedly restricted repertoire of activity and interest as well as repetitive patterns of behavior. "BIRC6 is associated with various psychiatric and neurological disorders, such as Autism, AD, and cognitive functions." (PMID 39963874, 2025).
bacteremia (1 paper, 2023). "The occurrence of the rs183868412 variant in combination with the increased expression of the BIRC6 gene may determine a greater morbidity of prematurely born children and increase the risk of bacteremia." (PMID 36768802, 2023).
bladder tumors (1 paper, 2024). "Circ-BIRC6 is involved in enhancing the progression and metastasis of bladder tumor cells, and its depletion is key in reducing tumor malignancy." (PMID 38733529, 2024). "As a result, silencing circ-BIRC6 is advantageous in reversing EMT in bladder tumors." (PMID 38733529, 2024).
cholangiocarcinoma (1 paper, 2023). A carcinoma that arises from the intrahepatic biliary tree (intrahepatic cholangiocarcinoma) or from the junction, or adjacent to the junction, of the right and left hepatic ducts (hilar cholangiocarcinoma). "Based on previous bioinformatics analysis, we screened the protein BIRC6, which may affect the progression of cholangiocarcinoma cells with XPO1." (PMID 36200270, 2023).
chronic myelogenous leukemia (1 paper, 2017). "Our phosphoproteomic analysis of an imatinib-resistant chronic myelogenous leukemia (CML) cell line (MYL-R) identified increased amounts of a BIRC6 peptide phosphorylated at S480, S482, and S486 compared to imatinib-sensitive CML cells (MYL)." (PMID 28520795, 2017).
Cognitive impairment (1 paper, 2023). Abnormal cognition is characterized by deficits in thinking, reasoning, or remembering. "In conclusion, combined with the results of the literature search and bioinformatic analysis, we believe that the three genes, BIRC6, TGFB1, and PSEN1, have a clear correlation with T2DM and cognitive impairment, which can be used as target genes for disease prediction in the future." (PMID 37189611, 2023).
colon cancer (1 paper, 2012). "BIRC6 expression protected colon cancer stem cells from the cytotoxic effects of oxaliplatin and cisplatin." (PMID 23211188, 2012).
COVID-19 (1 paper, 2022). A disease caused by infection with severe acute respiratory syndrome coronavirus 2. "Additionally, we found 44, 42, and 53 up-DEGs that were notably associated with mild, moderate, and severe COVID-19, and there were six significant common genes across three phases of COVID-19, including TCF7, GZMH, RAB5IF, CCND2, BIRC6, and NDUFAF3." (PMID 35172892, 2022).
glaucoma (1 paper, 2014). Increased pressure in the eyeball due to obstruction of the outflow of aqueous humor. "The goal of the current study is to investigate the role of these two genes, protein disulphide isomerase A member 5 (PDIA5) and baculoviral IAP repeat containing 6 (BIRC6), in different forms of glaucoma." (PMID 25118708, 2014).
large intestine carcinoma (1 paper, 2023). "Of these, two missense variants—2:32525512-32525512 (BIRC6) and 4:54727895-54727895 (KIT)—had been previously reported as mesothelioma and large intestine carcinoma." (PMID 37469410, 2023).
lung adenocarcinoma (1 paper, 2022). A carcinoma that arises from the lung and is characterized by the presence of malignant glandular epithelial cells. "Immunoblot results from lung adenocarcinoma cell line showed that knockdown of NFYC-AS1 did reduce the BIRC6 protein level, suggesting a possible regulation of BIRC6 expression by NFYC-AS1." (PMID 36105077, 2022).
oral cancer (1 paper, 2023). "However, additional studies involving larger sample sizes are required to validate these results and gain a more comprehensive understanding of the underlying mechanisms through which BIRC6 contributes to the development of oral cancer." (PMID 38066801, 2023).
renal carcinoma (1 paper, 2025). A carcinoma arising from the epithelium of the renal parenchyma or the renal pelvis. "The evaluation of BIRC6 expression using IHC, Western blotting, and reverse transcription-quantitative polymerase chain reaction (PCR) in renal cancer tissues, compared with adjacent non-cancerous tissues and paired normal tissues, showed a higher expression in carcinoma tissues." (PMID 40510224, 2025).
salivary gland adenoid cystic carcinoma (1 paper, 2023). An adenoid cystic carcinoma arising from the salivary gland. "However, low BIRC6 expression (0.0%) in salivary gland adenoid cystic carcinoma suggests a dual function for BIRC6 in carcinogenesis." (PMID 38066801, 2023).
salivary gland tumors (1 paper, 2025). "Therefore, in the present study, we aimed to evaluate the expression level and percentage of BIRC6 in three types of salivary gland tumors and the correlation of BIRC6 overexpression with the clinicopathological features." (PMID 40510224, 2025). "However, a role for BIRC6 in salivary gland tumors has not been reported so far." (PMID 40510224, 2025).
schizophrenia (1 paper, 2022). A major psychotic disorder characterized by abnormalities in the perception or expression of reality. "Our results suggest significant relationships between the increased expression of apoptosis genes (Bcl2, Birc6, Bax, Casp3, and Casp9) in peripheral blood lymphocytes and immune system dysregulation in patients with schizophrenia." (PMID 35566680, 2022).
Sepsis (1 paper, 2022). Sepsis is defined as life-threatening organ dysfunction caused by a dysregulated host response to infection. "In keeping with a role for BIRC6 in autophagy and apoptosis in sepsis, our data identify a role for genetic variation at BIRC6 in determining risk of invasive infection secondary to a broad range of bacteria." (PMID 35866869, 2022). "A more complete understanding of the role played by genetic variation at BIRC6 plays in the pathogenesis of sepsis in African children will require more detailed expression and functional studies in African populations." (PMID 35866869, 2022). "The locus identified modifies splicing of BIRC6 in stimulated monocytes, implicating regulation of apoptosis and autophagy in the pathogenesis of sepsis in Kenyan children." (PMID 35866869, 2022). "In keeping with a role for regulators of apoptosis in the pathogenesis of sepsis, members of the IAP family, including NAIP/BIRC1 and BIRC3, are downregulated in immune cells in patients with sepsis, as is the BIRC6 ubiquitination target SMAC." (PMID 35866869, 2022). "As above, BIRC6 regulates autophagy through its interaction with LC3, and overexpression of LC3B limits inflammation and tissue injury in a mouse model of sepsis." (PMID 35866869, 2022).